MTOR (mechanistic target of rapamycin kinase)
Diseases named in the same sentence as MTOR in open-access papers (continued):
Sharing a sentence is not in itself a finding about the gene and the disease.
cancer (continued). "Elevated mTOR/p-mTOR expression is increasingly recognized in association with specific cancers." (PMID 41219936, 2025). "Furthermore, increased mTor activity was shown to cause rDNA CN reduction in mouse hematopoietic stem cells, and some cancer types with high mTor activity are associated with low rDNA CN33." (PMID 39755735, 2025). "Additionally, they exert influence over drug transporters and multidrug resistance proteins while also upregulating cancer-associated signaling pathways, including mTOR and Wnt/β-catenin." (PMID 39940704, 2025). "Additionally, our analysis revealed longer PFS in patients with high NK cells, interferons, and RB1 mutations, whereas high cancer-associated fibroblasts levels and mutations in the mTOR signaling pathway and PTPRD were indicators of shorter PFS." (PMID 39962074, 2025). "Similarly, another signaling pathway commonly activated by KRAS mutations and present across multiple cancer types is the PI3K/AKT/mTOR signaling pathway via PI3K and Ras activation by phosphorylation." (PMID 39941724, 2025). "However, certain epigenetic regulators reduce PTEN expression or directly activate AKT, causing uncontrolled PTEN/AKT/mTOR signaling that desensitizes cancer cells to sorafenib." (PMID 41298358, 2025). "Phosphoinositide 3-kinase PI3K-Akt-mTOR is one of the primary autophagy regulators, and other signalling pathways and molecules have also been implicated in controlling drug-induced autophagy that affects the effectiveness of anti-cancer therapy." (PMID 41151762, 2025). "In light of its myriad functions, the mTOR pathway is widely considered to be a central regulator of cellular and physiological homeostasis, and dysregulation of mTOR signaling has been implicated in many cancers." (PMID 38915098, 2024). "Another hallmark of cancer with the involvement of Hsp60 is the sustained proliferation, mediated by this protein mainly by interacting with the following two signaling pathways: the mTOR and MAPK cascades." (PMID 38672583, 2024). "In addition, mutations in mTOR itself have been identified in diverse subtypes of cancer, providing further evidence for the involvement of mTOR in the development of tumors." (PMID 38539200, 2024). "Second, it could act as a component of lipid rafts, and so as a molecule that increases the transduction response of pathways such as Ras/MAPK or PI3K/Akt/mTOR that have been hugely implicated in cancer promotion and progression." (PMID 38893271, 2024). "Members of the PI3K/Akt/mTOR pathway are commonly mutated in cancer." (PMID 38672636, 2024). "In addition, our data showed that abemaciclib treatment by inhibiting pAKT affects also the mTOR signaling cascade, which is implicated in the abnormal growth and survival of cancer cells." (PMID 39011477, 2024). "mTOR regulates cell proliferation and has also been associated with cancers." (PMID 39337548, 2024). "Dysregulation of mTOR has been implicated in the development of various types of cancers." (PMID 39000261, 2024). "Interestingly, it was found that drugs targeting phosphoinositide 3-kinase/mammalian target of rapamycin (PI3K/mTOR) signaling were broadly associated with multiple eRNAQTL-eRNAs across different cancer types." (PMID 38863031, 2024). "Numerous genes involved in stress responses, cell proliferation, metabolism, and longevity interact with each other, and many of them converge on the IIS/mTOR signaling pathways; reduction in IIS/mTOR activities is associated with fitness and cancer resistance." (PMID 39056774, 2024). "In addition to the high frequency mutated genes in TCGA, the mutation frequencies of PIK3CA were high in cancer tissues from our cohort, thus suggesting possible activation of the PI3k/Akt/mTOR pathway." (PMID 38886866, 2024). "Additionally, Loss of miRNA-204 induces the migration and invasion of cancer cells through activation of AKT/mTOR/Rac1 signaling and actin reorganization." (PMID 38965615, 2024).
cancer (continued). "The PI3K/Akt/mTOR pathway, besides being involved in regulating apoptosis is also implicated in promoting angiogenesis in cancer cells and CH intervention is suggested to obstruct such pathways efficiently, thereby limiting their capacity to establish secondary tumors in distant organs." (PMID 38966181, 2024). "Besides being linked to promoting cancer by mTOR hyperactivation, this trait is used in sports nutrition to increase muscle growth or in conditions caused by prior muscles loss." (PMID 39198298, 2024). "Additionally, NEDD4 is a proto-oncogene that downregulates PTEN expression, thereby impacting the PI3K/AKT/mTOR pathway that is implicated in multiple types of cancers." (PMID 39726707, 2024). "Dysregulation of mTOR signaling is commonly implicated in human diseases, including cancer." (PMID 38654109, 2024). "The deregulation of mTOR and associated proteins in its signaling pathway results in aberrant cellular growth, proliferation, migration, and survival, contributing to both the pathogenesis and therapy resistance of many cancers." (PMID 38474373, 2024). "Additional therapeutic opportunities may be available in targeting other pathways such as mTOR inhibitors, photodynamic therapy, or cancer-associated fibroblasts and tumor-associated macrophages." (PMID 39199674, 2024). "Additionally, certain signaling pathways associated with both T2DM and cancer including PI3K/AKT/mTOR are used as therapeutic targets for various types of cancers." (PMID 39410536, 2024). "Furthermore, certain pathways such as the PI3K/AKT/mTOR pathway, which are associated with glucose metabolism, frequently exhibit molecular alterations in various cancer subtypes." (PMID 39410536, 2024). "Ki67 is a marker of cell proliferation associated with activation of mTOR in cancer cells." (PMID 39164530, 2024). "Given the dual role of mTOR inhibitors in suppressing posttransplantation rejection and reducing the risk of posttransplantation tumorigenesis, they are essential for the prevention and treatment of specific types of posttransplantation cancers." (PMID 39224537, 2024). "Dysregulated MTOR signaling has been implicated in the progression of several diseases including chronic obstructive pulmonary disease, pulmonary arterial hypertension, idiopathic pulmonary fibrosis, heart failure, and cancer." (PMID 39510184, 2024). "Patients with cancer bearing these mutations may be effectively treated with therapies that combine ferroptosis induction with mTOR inhibition." (PMID 39353906, 2024). "Thus, inhibition of mTOR not only plays an important role in the control of cancer progression in HCC but also is closely associated with the formation of VETC." (PMID 38250695, 2024). "Frequently, mTOR dysregulation is associated with the development of various types of cancer." (PMID 39200267, 2024). "It was found that the PI3K/AKT/mTOR signaling pathway is associated with multiple types of cancers." (PMID 39519654, 2024). "Height is implicated in many biological pathways such as skeletal growth, fibroblast growth factor (FGF) signaling, WNT (Wingless/Integrated) signaling, regulation of β-catenin, mammalian target of rapamycin (mTOR) signaling, and associates with overall cancer risk and mortality." (PMID 38489391, 2024). "Hyperactivating mutations in mTOR are found in various cancers and could indicate whether patients would benefit from mTOR inhibitors." (PMID 38270460, 2024). "Thus, TQ administration led to the inhibition of the JAK/STAT and PI3 K/AKT/mTOR signaling pathways, which stimulate c-Myc expression and are associated with the inhibition of proliferation and induction of apoptosis in cancer cells." (PMID 39769174, 2024). "The PI3K/AKT/mTOR pathway is frequently overactivated in various tumors and is associated with the most common mutated genes in tumors and related to the progression, metastasis, and resistance of malignant tumors." (PMID 39857585, 2024).
cancer (continued). "Stress includes an increase in the number of cancer cells, chemotherapy, radiation, hypoxia, and the accumulation of toxic waste, which cause the inactivation of mammalian target of rapamycin (mTOR) and the activation of AMP-activated protein kinase (AMPK) to induce autophagy." (PMID 39596291, 2024). "Additionally, these amino acids can modulate cancer-associated signaling pathways, such as mTOR, and regulate immune responses, particularly the function of T cells." (PMID 38613073, 2024). "To examine biological pathways, using all significantly altered genes, we performed Gene Ontology term analysis, identifying upregulation of pathways associated with autophagy, cell division, and signaling—including by Rho GTPases and mTOR, both implicated in cancer." (PMID 38126767, 2024). "Furthermore, TIMP1 is implicated in the regulation of the PI3K/Akt/mTOR pathway, where it inhibits cancer cell apoptosis while promoting cancer cell migration and invasion." (PMID 39436133, 2024). "Moreover, we observed a generalized depression of the mTOR pathway, which is generally regarded as a hallmark of dormancy in cancer cells." (PMID 39497135, 2024). "In cancer, upregulation of mTOR signaling may stimulate tumor growth and metastasis; indeed, mutations in the mTOR signaling pathway have been documented in various cancers." (PMID 39107687, 2024). "The subnetwork analyses showed that NEAT1, MALAT1, and OIP5-AS1 are associated with genes involved in cancer-related pathways, including the "mTOR signaling pathway," "AMPK signaling pathway", and "PI3K-Akt signaling pathway", as identified in KEGG pathway analysis." (PMID 39246994, 2024). "In this review, we demonstrate the association between the mTOR pathway and cancer, including CSCs." (PMID 39349424, 2024). "LKB1 is an established tumour suppressor and IL11-mediated inactivation of LKB1, through its sequential phosphorylation at S325A (ERK) and S428A (P90RSK), leads to AMPK inactivation and mTOR activation, this sequence of events is linked with cancer cell proliferation." (PMID 38054591, 2023). "Therefore, we made use of the Cancer Dependency Map by focusing on the genes encoding the mTOR components MTOR, RPTOR, and RICTOR." (PMID 37642941, 2023). "Similarly, SRPK2 inhibition and/or dual inhibition of mTOR and O‐linked β‐N‐acetylglucosamine (O‐GlcNAc) in metabolic syndromes or cancer cells dependent on upregulated lipid metabolism has been proposed as a potential anti‐cancer therapy." (PMID 37607329, 2023). "The phosphoinositide 3-kinase (PI3K)/AKT/mammalian target of rapamycin (mTOR) pathway appears to be an attractive target for anticancer therapy due to the fact that, in majority of cancers, it is associated with aggressive phenotypes, chemoresistance, and poor prognosis." (PMID 38201468, 2023). "The mTOR signaling pathway plays an important role in many physiological processes, and abnormalities in it are implicated in the pathogenesis of many diseases, including cancer." (PMID 37228652, 2023). "Hence, modulation of p-ERK/ERK along with the mTOR and its associated signals leads to apoptotic cell death in cancer cells." (PMID 36737760, 2023). "The mTOR signaling pathway has been implicated in drug resistance in cancer." (PMID 37140396, 2023). "As mTOR is frequently activated in cancer in a manner that affects drug susceptibility, our clusters might reflect variations in cellular metabolism that could alter drug susceptibilities in AML samples." (PMID 36599821, 2023). "Increased activation of mTOR is associated with worse survival in several types of cancer." (PMID 37486536, 2023).
cancer (continued). "Hence, we aimed to study the impact of such endogenously expressed post-translationally modulated PTEN and its functional importance in terms of its therapeutic possibilities as an upstream master regulator of the mTOR pathway in KSHV-associated cancer cells." (PMID 37602330, 2023). "Although no evaluation was performed on the PI3K downstream factors, the observed apoptosis, cell cycle arrest, and subsequent suppressed progression of different cancers imply that mTOR downstream factors that cause apoptosis and cell death must have been activated by treatment with CGs." (PMID 37584722, 2023). "Interestingly, an additional molecular mechanism underlying the anti-cancer activity of 5-FU is connected with mTOR inhibition." (PMID 37284849, 2023). "Understanding these pathways might greatly impact the development of novel medications and treatments for illnesses including cancer, metabolic disorders, and muscle wasting caused by mTOR signaling failure (Kim JH." (PMID 38046946, 2023). "Pathway enrichment analysis identified training in cancer survivors evoked a predominantly hypomethylated signature in pathways associated with cell cycle, DNA replication/repair, transcription, translation, mTOR signaling, and the proteosome." (PMID 36542473, 2023). "In addition to altered differentiation, aberrant proliferation is a hallmark of AML and is regulated by AKT/mTOR signaling in a variety of cancers." (PMID 37665633, 2023). "However, there are significant challenges associated with bioactive the PI3-kinase/Akt/mTOR inhibitors, which have limited their uses in cancer chemoprevention development." (PMID 36721812, 2023). "However, few studies have been conducted to clarify how the mTOR signal associated with therapeutic resistance in CRC is activated during exposure to anti-cancer drugs." (PMID 36768934, 2023). "The other cancer where mTOR is highly mutated is endometrioid carcinoma (12.63%)." (PMID 37513916, 2023). "In addition, KEGG enrichment and GSEA analyses of the TCGA-KIRC dataset suggested that TRIM15 was closely associated with the VEGF signaling pathway, cancer-related pathways, and the mTOR signaling pathway." (PMID 36670097, 2023). "Importantly, in this type of cancer there is a high prevalence of activating PI3K/AKT/mTOR pathway alterations linked to tumor cell survival and tumorigenesis, again highlighting the possible role of Kidins220 in cell viability through this cascade." (PMID 37542079, 2023). "Interestingly, normal uterine epithelial cells have been shown to harbor cancer-driver alterations in genes associated with the mTOR pathway." (PMID 37627318, 2023). "Interestingly, when expanding the drug search to other types of cancer, PanDrugs2 suggests MTOR inhibitors like everolimus and sirolimus due to the presence of an MTOR oncogenic mutation." (PMID 37207338, 2023). "Similarly, palmitoyl-acyltransferase ZDHHC23 displayed a positive association with DNA damage and mTOR pathways in eight and three cancer types, respectively." (PMID 37978524, 2023). "Since mTOR signaling is broadly implicated in cancer, metabolic disease, and neurological diseases, dual inhibition of the mTOR signaling pathway through gene therapy may be the most promising clinical strategy beyond neuropathic pain." (PMID 37958901, 2023). "PI3K/Akt/mTOR has been linked to carcinogenesis and progression of cancer." (PMID 38053170, 2023). "Recent studies have shown that the constitutive activation of the mTOR pathway, due to genetic changes like mutations, amplifications, or deletions in mTOR itself, its complexes (mTORC1 and mTORC2), or its upstream targets, plays a role in aging, neurological disorders, and various human cancers." (PMID 38275385, 2023).
cancer (continued). "Mutations or overexpression of growth factor receptor (EGFR) or human growth factor receptor 2 (HER2), inactivating mutations in mTOR regulators gene such as TSC1 and TSC2, as well as the activating mutations in mTOR itself, are also detected across cancer types." (PMID 36765661, 2023). "Finally, CERS4 knockdown in doxorubicin-resistant MCF-7/ADR cells resulted in reduced activation of cancer-associated pathways (NF-κB, Akt/mTOR, β-catenin, and EMT) and diminished chemoresistance, accompanied by ABCB1 and ABCC1 downregulation." (PMID 37885013, 2023). "mTOR inhibitors can suppress the immune system, which may increase the risk of infections and compromise the body’s ability to fight against cancer cells." (PMID 37834408, 2023). "Also, how the dysregulated mTOR signaling is associated with aging, neurological disorders, and cancers." (PMID 37779156, 2023). "Even though here we focus on MAPK and PI3K/mTOR signaling cascades and the impact of their dysregulation, we note that the Hippo signaling pathway similarly feeds into the cell cycle and has been implicated in cell development and cancer." (PMID 37124926, 2023). "Since mTOR is associated with cellular growth and replication, inhibiting mTOR may be crucial in preventing the development of cancer." (PMID 36826066, 2023). "Patients that could benefit most from the use of mTOR inhibitors are those with a history of virally induced cancers and who are at risk of developing CMV disease or BK nephropathy." (PMID 35887051, 2022). "Therefore, the loss or mutation of TSC2 in some types of cancer is associated with increased mTOR activity and decreased AKT phosphorylation." (PMID 35745875, 2022). "Overall, necroptosis-related regulators could activate apoptosis, EMT, hormone ER, RAS/MAPK, RTK, and TSC/mTOR and inhibit cell cycle, DNA damage, and hormone AR pathways, which have been implicated in several cancers." (PMID 35748782, 2022). "Excessive lactate secreted by metabolism-reprogrammed cancer cells regulates immune responses via causing extracellular acidification, acting as an energy source by shuttling between different cell populations, and inhibiting the mTOR pathway in immune cells." (PMID 36698888, 2022). "Most cancers driven by PI3K/AKT/mTOR signaling aberrations are marked by PI3K kinase mutations." (PMID 36077798, 2022). "In addition, PI3K/AKT/mTOR is one of the most mutated signaling pathways in human cancers, usually correlated with the loss of PTEN and mutations in PIK3CA (encoding PI3K-p110α) and AKT1." (PMID 36077529, 2022). "However, at present, the main therapeutic application of mTOR is in cancer, especially focused on the classic PI3K/AKT/mTOR signaling pathway, implicated in cancer, which has been widely studied to develop treatments for cancer." (PMID 36012464, 2022). "Indeed, mTOR is implicated in increased glycolysis and glutamine metabolism proliferation cancer cells." (PMID 36670936, 2022). "Notably, seven genes associated across more than one cancer type, of which three (BRCA1, EP300, MTOR) associated with the same somatic mutational component across two different cancer types." (PMID 35764656, 2022). "Thus, alteration of the PI3K/Akt/mTOR pathway is strongly implicated in cancer pathogenesis, and targeting the effectors of this pathway is a promising therapeutic approach." (PMID 36319631, 2022). "The PI3K/AKT/mTOR pathway is closely associated with growth, survival, and the invasion of cancers." (PMID 35918763, 2022). "Prior studies established the role of mTORC1 in promoting invasion and cancer metastases; thus, the robust mTOR inhibition exerted by GZ17-6.02 may underlie its ability to suppress the invasiveness of GSCs." (PMID 35456993, 2022).